ABCB1 (ATP binding cassette subfamily B member 1)
Diseases named in the same sentence as ABCB1 in open-access papers (continued):
Sharing a sentence is not in itself a finding about the gene and the disease.
cancer (continued). "Based on this observation, a specific set of probucol derivatives and analogues, either commercially available or obtained by chemical synthesis, were examined for their ability to inhibit the activity of ABCB1 in cancer cells." (PMID 36674503, 2023). "Being aware that numerous EGFR inhibitors had been previously discovered as modifiers of ABCB1 and/or ABCG2, we explored the potential of furmonertinib to enhance chemosensitivity in multidrug-resistant cancer cells that overexpress ABCB1 or ABCG2." (PMID 37762275, 2023). "The expression of the drug efflux pump ABCB1 correlates negatively with cancer survival, making the transporter an attractive target for therapeutic inhibition." (PMID 36982374, 2023). "It is crucial to note that many studies have shown that EMT is a common cause of sorafenib resistance in HCC and poor disease-free survival and that snails can directly increase the ABC transporter ABCB1 in cancer cells, leading to treatment resistance." (PMID 37626693, 2023). "Since osimertinib had previously been identified as a substrate of both ABCB1 and ABCG2, we assessed the susceptibility of various cancer cell lines to furmonertinib." (PMID 37762275, 2023). "The ABC transporters (ATP-binding cassette), in particular, the multidrug resistance protein 1 (MDR1 or ABCB1) can resist cancer conventional treatment, such as chemotherapy." (PMID 37896762, 2023). "A chromosomal amplification event at 7q11.2-21 has been correlated to increased ABCB1 copy number and consequent P-glycoprotein expression in paclitaxel-resistant cancer cells." (PMID 35681784, 2022). "In cancer, ABCB1 mediates the effectively efflux of its substrate chemotherapeutic agents, including doxorubicin (Dox), vincristine, and paclitaxel, out of the cells." (PMID 36104708, 2022). "Taken all together, these data indicated that ARS-1620 is a substrate for ABCB1, and the potential influence of ARS-1620-related cancer therapy on ABCB1-overexpressing cancer cells should be considered in future clinical applications." (PMID 35281897, 2022). "The overexpression of ATP binding cassette subfamily B member 1 (ABCB1) or ATP binding cassette subfamily G member 2 (ABCG2) decreased the sensitivity of human cancer cells to ACY-241." (PMID 36076996, 2022). "Given that Tx-R cancer sublines utilized in the present study exhibited high expression levels of ABCB1, we also examined BGJ 398′s ability to inhibit the activity of this ABC transporter." (PMID 35327403, 2022). "Chemotherapeutic agents have been reported to stimulate the secretion of EVs containing various biologically active substances, such as ABCB1, annexin A6, miR-9-5p, miR-203a-3p, and miR-195-5p, promoting chemoresistance and cancer invasiveness." (PMID 35326493, 2022). "The activity of the P-glycoprotein (P-gp) transporter encoded by the ABCB1 gene confers resistance to anticancer drugs and contributes to cancer-related mortality and morbidity." (PMID 36364209, 2022). "The desensitization effect of ARS-1620 was remarkably intensified in both drug-induced ABCB1-overexpressing cancer cells and ABCB1-transfected cells as confirmed by cell viability assay results." (PMID 35281897, 2022). "ChIP-seq analysis revealed that differentially accessible enhancers in aggressive drug-resistant cells had a higher FOXC1 binding, which regulated the expression of adjacent cancer-relevant genes like ABCB1 and ID3." (PMID 35406487, 2022). "Multidrug resistance (MDR) is connected with overexpression of drug efflux transport ATP-binding cassette subfamily B member 1 (ABCB1) in cancer cells." (PMID 36438923, 2022). "Further, certain standard cancer drugs are transported using P-glycoprotein, also known as ‘multidrug resistance protein’ 1 (MDR1) or ‘ATP-binding cassette sub-family B member’ 1 (ABCB1)." (PMID 35630688, 2022). "Uptake of ABCB1 by recipient cells enhances drug efflux and the acquisition of resistance to the cancer treatment." (PMID 35646668, 2022).
cancer (continued). "Its treatment significantly sensitized ABCB1 or ABCG2 overexpressing cancer cells by impairing the functions of ABCB1 and ABCG2 in these transporter-amplified cancer cells." (PMID 35053461, 2022). "Collectively, we show here for the first time the off-target effect of BGJ 398 on ABCB1-overexpressing multi-drug resistant Tx-R cancer cells." (PMID 35327403, 2022). "With the aim to characterize other efficient and safe targets that can be used to reverse ABCB1-mediated MDR in cancers, we further investigated the signaling pathways involved in the PI3K110α and 110β regulated ABCB1 expression." (PMID 35459184, 2022). "This was in concordance with a significant increase of ABCB1 (i.e., P-glycoprotein) expression in all Tx-R cancer sublines when compared to parental cancer cells." (PMID 35327403, 2022). "We next used elacridar, a third-generation inhibitor that has been shown to inhibit ABCB1 activity and overcome drug resistance in cancer models." (PMID 36038196, 2022). "Currently, drug development strategies targeting ABCB1-mediated drug resistance in cancer mostly combine ABCB1 inhibitors with substrate drugs to re-establish drug sensitivity in the drug-resistant cells." (PMID 35721223, 2022). "Cancer cells upregulate ABCB1 expression as an adaptive response to evade chemotherapy-mediated cell death." (PMID 36233525, 2022). "Cancer stem cell markers, such as Oct-4, Nanog, ABCB1, and ALDH1A1, were significantly reduced in MCF-7 cells treated with kaempferol and docetaxel." (PMID 35986346, 2022). "Inhibiting of ABCB1 function or expression can reverse ABCB1-mediated MDR in cancer cells, which can increase the efficacy of chemotherapy." (PMID 35418870, 2022). "The clinical significance of pharmacogenetic biomarkers OPRM1 rs1799971, COMT rs4680 and ABCB1 (rs1045642, rs1128503, and rs2032582) should be further explored in future studies to improve precision pain management amongst Asian patients with cancer pain." (PMID 36422103, 2022). "The first ABC transporter (ABCB1, or P-glycoprotein) in a eukaryote was found in humans (Homo sapiens), and it is also the first protein found in humans that is resistant to drugs treating cancer." (PMID 35206711, 2022). "All compounds were tested for their biological activity against MDR on ABCB1-dependent MDR cancer cell line HepG2/ADR, and compounds 60–62 were identified as potent MDR modulators." (PMID 35418870, 2022). "ABCB1 has been attested to have a close relationship with multidrug resistance; thereby, knocking out ABCB1 in drug-resistant cancer cell lines made those cells more responsive to chemotherapies." (PMID 36176764, 2022). "We also determined the effect of palbociclib on the expression of the ABCB1 protein in SW620/Ad300 cancer cells, which also overexpress the ABCB1 transporter." (PMID 35350768, 2022). "Overall, our results indicate that palbociclib is a substrate for the ABCB1 transporter and that its in vitro anticancer efficacy is significantly decreased in cancer cells overexpressing the ABCB1." (PMID 35350768, 2022). "In particular, several groups of anti-cancer drugs are known as the substrates of ABCB1 and include vinca alkaloids, anthracyclines, epipodophyllotoxins, and taxanes." (PMID 35327403, 2022). "Although ABCB1 and other ABC transporters have been implicated as markers of “cancer stem cells”, they are also transcriptional targets of PI3K/AKT signaling, which is upregulated by carboplatin treatment." (PMID 36230889, 2022). "ABCB1/Pgp is also an important factor in cancer multidrug resistance, potentially protecting the transporter-expressing tumor cells from targeted chemotherapeutic agents." (PMID 36142507, 2022). "At present, the project focusing on the function of ribociclib in inhibiting the ABCB1 mediated-MDR in cancers are undergoing in our laboratory." (PMID 35459184, 2022).
cancer (continued). "The multidrug resistance protein 1 (ABCB1) is often mutated in BRCA, and is related to the epithelial-to-mesenchymal transition mechanism and cancer metastasis." (PMID 35739271, 2022). "These inhibitors sensitize the ABCB1 overexpressing cancer cells to the substrate chemotherapeutic drugs." (PMID 36147477, 2022). "Nevertheless, most of fourth-generation ABCB1 inhibitors have been evaluated in cancer cells in vitro, and their efficacy and safety in vivo have not been determined." (PMID 35418870, 2022). "The co-culture of CAFs in conditioned media from gastric cancer cells showed an increased level of phosphorylated AKT, PI3K, p65, lkb and ABCB1, together with the activation of NFkB that increased the resistance to cisplatin in cancer cells." (PMID 36114508, 2022). "Recently, σ2 receptor ligands have been shown to have promising cytotoxic effects against cancer cells and to modulate the activity of P-glycoprotein (ABCB1) in vitro experiments, but their specific effects and mechanisms remain to be elucidated." (PMID 36120340, 2022). "In ATC, high expression levels of ABCB1, ABCC1 and ABCG2 observed in several cell lines and tissues, were associated with cancer drug resistance." (PMID 35837087, 2022). "Based on single gene knockout, we studied the regulation of CDK6-PI3K axis on ABCB1-mediated MDR in human cancer cells." (PMID 35459184, 2022). "When overexpressed in cancer cells, ABCB1 produces an MDR phenotype to various chemotherapeutic drugs, including paclitaxel, doxorubicin, and tyrosine kinase inhibitors (TKIs) such as GSK-1070916 and TAK243." (PMID 35350768, 2022). "This coupling enables the transfer of Zn2+ from fibroblasts to cancer cells, inducing ABCB1-mediated drug extrusion and chemoresistance." (PMID 36207295, 2022). "Acting as a Zn2+ reservoir, ZIP1+ fibroblasts absorb and transfer Zn2+ to cancer cells, leading to ABCB1-mediated chemoresistance." (PMID 36207295, 2022). "Knockout of the cdk6 gene unveiled a novel targeting pathway for overcoming ABCB1-mediated MDR in cancers." (PMID 35459184, 2022). "Here, we report that infigratinib (BGJ 398), a potent FGFR1-4 inhibitor, restores sensitivity of a broad spectrum of ABCB1-overexpressing cancer cells to certain chemotherapeutic agents, including paclitaxel (PTX) and doxorubicin (Dox)." (PMID 35327403, 2022). "Given the BGJ 398 reversed sensitivity of ABCB1-overexpressing Tx-R cancer cells to PTX and Dox due to impaired efflux of these chemotherapeutic agents, we also examined its potential binding site in ABCB1." (PMID 35327403, 2022). "A number of cancers acquire resistance to drug treatment by overexpressing the ATP Binding Cassette transporter ABCB1 (p-glycoprotein)." (PMID 35669422, 2022). "The multidrug-resistant phenotype in cancer that mediates MDR also heavily relies on P-glycoprotein (P-gp/ABCB1)." (PMID 36613493, 2022). "It has been demonstrated that crizotinib is a substrate of the P-glycoprotein (P-gp, ABCB1) transport protein, whose overexpression on cancer cells accounts for their pharmacoresistance." (PMID 36559018, 2022). "In vivo experiment demonstrated the function of cdk6 in maintaining ABCB1-mediated drug resistance in cancers." (PMID 35459184, 2022). "In this study, we investigated the connection between novel emerged KRAS-G12C inhibitor, ARS-1620, and ABCB1-overexpressing cancer cells." (PMID 35281897, 2022). "Collectively, we show here for the first time that BGJ 398 reverses the sensitivity of MDR-overexpressing cancer cells to certain chemotherapeutic agents due to inhibition of their efflux from cancer cells via ABCB1-mediated mechanism." (PMID 35327403, 2022). "CDK6-PI3K as a new target signaling axis to reverse ABCB1-mediated MDR is reported for the first time in cancers." (PMID 35459184, 2022). "MTT assay was carried out to measure cytotoxic effect of MRTX849 and its circumvention of MDR in ABCB1-overexpressing cancer cell lines." (PMID 36104708, 2022).
cancer (continued). "They seem to be highly effective in overcoming the ABCB1-dependent resistance of cancer cells in vitro." (PMID 35008510, 2021). "The third generation of ABCB1 inhibitors showed some efficacy in clinical trials, but their high toxicity has compromised their use for cancer treatment." (PMID 33990571, 2021). "In this review, the contribution of canonical and non-canonical developmental signaling pathways in transcriptional regulation of ABCB1 to confer MDR in cancer is delineated." (PMID 35582031, 2021). "In recent years, more ABC transporters have been identified to be related with MDR in cancer besides ABCB1, ABCG2, and ABCC1." (PMID 33593355, 2021). "Further, microRNAs inhibit cancer cell proliferation and metastasis, and melatonin-induced miR-392a and miR-34b increase cancer cell apoptosis by inhibiting ABCB1/ABCB4 activity." (PMID 33546749, 2021). "Overexpression of ABCB1 contributes to chemotherapy resistance of cancer cells in vitro and was related to worse survival of cancer patients in several studies." (PMID 34858183, 2021). "The results showed that stable knockout of ABCB1 gene by the CRISPR/Cas9 system was achieved in the MDR cancer cells." (PMID 34977876, 2021). "Ineffective chemotherapy treatment is one of the greatest challenges posed by modern cancer treatment, which in part, results from upregulation of broad range transporters such as ABCB1, in many cancer cells." (PMID 35582031, 2021). "Our rationale to focus on this gene is that ABCB1 has been known to be related to chemoresistance in many different types of cancer." (PMID 34094978, 2021). "Experimental gene therapies using ribozymes, antisense oligonucleotides, as well as small interfering RNAs have been developed and demonstrated success in reversing MDR in cancer cells by downregulating ABCB1 expression." (PMID 34977876, 2021). "High ABCB1 expression has been observed in SP cells in a number of cancer cell lines compared to other cells." (PMID 34051847, 2021). "The encapsulated ABCB1 siRNA hyaluronic acid (HA) nanoparticles targeted cancer cells overexpressing surface protein CD44." (PMID 34771642, 2021). "We first examined the effect of TP-3654 on ABCB1-mediated resistance to doxorubicin, paclitaxel and colchicine, three well-known substrate drugs of ABCB1, in ABCB1-overexpressing NCI-ADR-RES, KB-V-1 cancer cells, and ABCB1-transfected MDR19-HEK293 cells." (PMID 34502348, 2021). "In many cancers, overexpression of P-glycoprotein (P-gp, ABCB1) contributes to the found multidrug resistance (MDR) phenotype." (PMID 34203998, 2021). "Tariquidar is a non-marketed, third-generation ABCB1 inhibitor, which was originally developed to overcome multidrug resistance in cancer patients and which has been re-purposed to inhibit ABCB1 at the BBB in an experimental setting." (PMID 34220523, 2021). "As the outcomes for applications of ABCB1 inhibitors in clinical settings have been disappointing, novel strategies to surmount ABCB1‐mediated cancer MDR, such as gene therapy approaches, are gaining more attention." (PMID 34977876, 2021). "In the literature, it is well described that ABCB1 overexpression produces MDR in different cancer cells inducing the decrease in the intracellular concentration of ABCB1 substrates, such as taxanes." (PMID 34360846, 2021). "The key role of canalicular ABC transporters in bile secretion is highlighted by their implication in a wide range of diseases such as cholestasis (ABCB4, ABCB11), sitosterolemia (ABCG5/G8), Dubin–Johnson syndrome (ABCC2) and cancer (ABCB1)." (PMID 33672718, 2021). "Increased expression of P-glycoprotein (P-gp), which is encoded by ATP-binding cassette subfamily B member 1 (ABCB1) gene, often contributes to ADR resistance in cancer." (PMID 34354052, 2021). "Published data showed that tangeretin has the ability to sensitize excessive ABCB1 expression cancer cells to chemotherapeutic agents through direct inhibition of ABCB1 transporter activity." (PMID 33748757, 2021).
cancer (continued). "ABCB1 relieves cancer cells from several chemotherapeutic drugs, including vinca alkaloids, anthracyclines, taxanes, and notably paclitaxel." (PMID 34065402, 2021). "ABCB1/MDR1 is an ATP-dependent efflux pump that decreases the intracellular concentration of a variety of anti-cancer drugs, leading to multidrug resistance in several types of cancer, including PCa." (PMID 33799432, 2021). "ABC transporter comprises ABCs (multidrug resistance-associated proteins (MRPs)), ABCB1 (P-glycoprotein/MDR1), and ABCG2 (BCRP/MXR/ABCP)) all were reported to be overexpressed in cancer developing the MDR." (PMID 34205602, 2021). "Nevertheless, several studies have investigated the role of various lncRNAs on Wnt/β-catenin signaling and ABCB1 expression in cancer." (PMID 35582031, 2021). "The development of cancer chemoresistance is upregulated by several ABC transporters including ABCB1, ABCC1, ABCC2, and ABCG2." (PMID 34066059, 2021). "In the past years, MDR1 (ABCB1, P-glycoprotein, and P-gp) and MDR-associated protein 1 (MRP1) were the most extensively investigated resistance proteins in cancer." (PMID 34869449, 2021). "We discovered that the overexpression of ABCB1 or ABCG2 significantly reduced the sensitivity of human cancer cells to citarinostat." (PMID 33807514, 2021). "As it is well-known that drug transporters play a crucial role in cancer drug resistance, we examined the expression levels of several drug transporters, including ABCB1 (MDR1), ABCC1 (MRP1), ABCG2/BCRP, and LRP/MVP, in MDA-MB-231Tx cells by RT-PCR." (PMID 34944868, 2021). "Another critical mechanism involves the increased outflow of drugs from cancer cells by upregulated transport proteins that rely on specific energy sources such as ABCB1, ABCC1, and ABCG2." (PMID 34306145, 2021). "Genetic alterations of the Wnt pathway components are found in most cancer studies on ABCB1 expression and MDR, which are under the control of Wnt signaling." (PMID 35582031, 2021). "ABCB1 was enriched in EVs from various drug-resistant cancer cells after chemotherapy and was associated with acquired resistance to docetaxel." (PMID 33995103, 2021). "As formerly mentioned, apigenin sensitized prostate, uterine, and breast cancer cells to DOX by ABCB1 inhibition." (PMID 34715860, 2021). "Recent studies have identified canonical and non-canonical GLI consensus sequences in multiple ABC transporters, including ABCB1, in chemoresistant cancer cells." (PMID 35582031, 2021). "P-glycoprotein (P-gp or ABCB1) is a transmembrane protein of great clinical interest due to its involvement in cancer multidrug resistance (MDR)." (PMID 35070633, 2021). "Three paradigm ABC transporter members, ABCB1 (P-gp), ABCC1 (MRP1) and ABCG2 (BCRP) appear to act as brothers in arms in promoting or causing MDR in a variety of therapeutic cancer settings." (PMID 33946618, 2021). "Of note, ABCB1 amplification was observed more frequently in cohort A (20.0%) and B (9.5%) compared to what has been previously reported in the Stand Up 2 Cancer database (~2%)." (PMID 34439209, 2021). "Efflux transporters (ETs) such as P-glycoprotein (P-gp, ABCB1), multidrug resistance-associated protein (MRP, ABCC), and breast cancer resistance protein (BCRP, ABCG2) actively pump anti-cancer drugs out of cancer cells." (PMID 33800412, 2021). "ABCB1, a well-known multidrug resistance protein, plays a vital role in chemoresistance in various types of cancers." (PMID 34336684, 2021). "When exposed to an anticancer drug, cancer cells alter their phenotypes to resist the drug by increasing the ATP binding cassette subfamily B member 1 (ABCB1) protein." (PMID 33921245, 2021). "Overexpression of ABC transporters, such as ABCB1, which efflux chemotherapeutic drugs, such as docetaxel, out of cancer cells is a widespread mechanism of resistance that plays a significant role in treatment failure, including in PCa." (PMID 33799432, 2021).